VIM (vimentin)
Diseases named in the same sentence as VIM in open-access papers (continued):
Sharing a sentence is not in itself a finding about the gene and the disease.
breast carcinoma (continued). "SMRwt breast cancer derived exosomes had Vimentin and Mortalin protein expression levels reduced to 46.56% and 45.64% for MDA-MB-231 and 61.56% and 35.99% for MCF-7." (PMID 35915218, 2022). "Connexins linked to N-cadherin, vimentin, Snail, and Zeb1 modulate CSC and EMT properties in breast cancer cells." (PMID 35464064, 2022). "Further, miR-Vimentin and miR-Mortalin breast cancer derived exosomes had Vimentin and Mortalin protein expression levels reduced to approximately 50% for MDA-MB-231 and MCF-7." (PMID 35915218, 2022). "We explored the function of GluOC in the EMT of breast cancer cells by assessing the levels of vimentin, N-cadherin, Snail and E-cadherin." (PMID 35413833, 2022). "In another breast cancer research, FOXA1 was found to downregulate EMT-associated markers, including E-cadherin, ZEB2, and vimentin, eventually preventing EMT progression." (PMID 36393971, 2022). "There were also correlations of Vimentin overexpression with breast cancers in NHW women, with the TNBC subtype and with Ki67, and an inverse correlation with E-cadherin." (PMID 36494865, 2022). "Previously, vimentin was reported to promote tumor metastasis through positive regulation of Axl (AXL Receptor Tyrosine Kinase) in breast cancer." (PMID 35359350, 2022). "Overexpression of vimentin correlates significantly with poor prognosis in several cancers, such as gastric cancer and breast cancer." (PMID 35320951, 2022). "The Nef SMR sequence interacts with cellular proteins, including mortalin and vimentin, and blocks breast cancer cell exosome release." (PMID 35915218, 2022). "Breast cancer derived exosomes E-cadherin protein levels were heightened > 100% for SMRwt, miR-Vimentin, and miR-Mortalin." (PMID 35915218, 2022). "More importantly, FMRP was shown to regulate mouse breast cancer metastasis by modulating the translation and stability of E-cadherin and Vimentin, respectively." (PMID 35534866, 2022). "For example, CPEB4 can promote breast cancer metastasis through upregulation of Vimentin and facilitate the migration and invasion of lung cancer cells through activation of the AKT pathway." (PMID 35317822, 2022). "Treatment with SMRwt of MDA-MB-231 and MCF-7 breast cancer cells lowered the protein expression of Mortalin to 27.66% and 60% as well as Vimentin to 14.12% and 23.68%." (PMID 35915218, 2022). "Upregulated ROR has been found to promote EMT progression in breast cancer cells by elevating vimentin, N-cadherin, MMP2, and MMP9." (PMID 36613528, 2022). "Our data suggested that downregulation of vimentin in breast cancer cell lines either expressing vimentin endogenously (MDA-MB-231) or ectopically (MCF-7FV), had a common set of DEGs." (PMID 36552797, 2022). "Breast cancer exosome protein expression levels of Mortalin and Vimentin mirrored the effects observed in the parental breast cancer cells treated with SMRwt, miR-Vimentin, and miR-Mortalin." (PMID 35915218, 2022). "Specifically, SMRwt treatment reduced mesenchymal markers Mortalin and Vimentin expression, while the epithelial marker E-cadherin expression was increased in breast cancer cells and breast cancer-derived exosomes." (PMID 35915218, 2022). "The epithelial components of breast carcinomas express E- cadherin, a proportion of them also show vimentin expression, while the mesenchymal components of breast carcinomas show vim expression." (PMID 35884609, 2022). "The overexpression of VIM has been reported to be correlated with epithelial cancers such as prostate cancer, CNS tumors, and breast cancer." (PMID 36378718, 2022). "In particular, VIM is also regarded as a marker of epithelial–mesenchymal transition (EMT), and the upregulation of VIM expression is observed in tumor types, such as prostate and breast cancers, malignant melanoma, and CNS tumors." (PMID 33917452, 2021).
breast carcinoma (continued). "Here, we figured out the detailed expression profile of HRD1 in breast cancer subtypes, deciphering its circRNA-regulated antimetastatic activity via targeting Vimentin." (PMID 33530981, 2021). "For example, simvastatin, a small-molecules inhibitor of cholesterol biosynthesis pathway, has been shown to induce apoptosis of MDA-MB-231 breast cancer cells through direct interaction between simvastatin and vimentin." (PMID 34203746, 2021). "In breast cancer, vimentin plays a significant role in the EMT processes, and its knockdown results in a reduction in genes linked with breast cancer invasion and the basal-like phenotype." (PMID 33919917, 2021). "Consistently, MTHFD2 has also been reported to affect cancer cell migration and invasion abilities by modulating vimentin expression in breast cancer and renal cell carcinoma." (PMID 34121323, 2021). "In parallel with these results, we build an in vitro EMT model utilizing the luminal breast cancer cell line MCF-7 to further testify the effect of HRD1-mediated Vimentin degradation." (PMID 33530981, 2021). "We also found a positive correlation between CMTM3 and CMTM7 expression with EMT score in breast cancer cells, and with Vimentin in TNBC patients." (PMID 33803139, 2021). "In summary, our findings suggest that circNR3C2 specially sponges miR-513a-3p, promoting HRD1-mediated degradation of Vimentin through ubiquitin-proteasome pathway thus ultimately suppressing tumor growth and metastasis of breast cancer." (PMID 33530981, 2021). "We found that overexpression of FOXO3a inhibited EMT in breast cancer cells, which was evidenced by increased E-cadherin expression in conjunction with a concomitant decreased in the expression of mesenchymal markers vimentin and N-cadherin." (PMID 33262463, 2021). "EMT was assumed to be a vital part of breast cancer migration, which is mainly manifested by diminishing E-cadherin expression while enhancing the expression of N-cadherin and vimentin." (PMID 34830111, 2021). "Breast carcinoma cells devoid of vimentin are reported to be less contractile and less effective in migration." (PMID 34638469, 2021). "Pioneering work by Hendrix and coworkers investigated genetic co-expression of keratin (K8 and K18) with vimentin in breast cancer and melanoma cell lines, showing some increase in 3D invasion due to altered integrin expression." (PMID 33691719, 2021). "CAF markers that have been associated with promotion of breast cancer tumor growth through several experiments include α-SMA, FAP, PDGFR-α, PDGFR-β, CD29, neural/glial antigen 2 (NG2), FSP1, vimentin, and podoplanin (PDPN)." (PMID 33808627, 2021). "LCN2 promotes EMT by upregulating mesenchymal markers such as fibronectin and vimentin in breast cancer cells while inhibiting the epithelial marker E-cadherin." (PMID 34588926, 2021). "Vimentin expression is upregulated during EMT in epithelial cells, and increased vimentin expression has been reported in various cancer cell lines and tissues, including prostate cancer, breast cancer, malignant melanoma, and colorectal cancer." (PMID 33919917, 2021). "The patient with the highest increase in activity of COX-2, PIK3CA, HER2, and Vimentin was diagnosed with colon cancer 84 months after treatment of breast cancer." (PMID 34590615, 2021). "Consistent with breast cancer cell migration, increased mRNA levels of N-cadherin and vimentin and decreased E-cadherin were found upon CT45A overexpression in MDA-MB-231 and MCF7 cells." (PMID 34503444, 2021). "Conversely, RNA silencing of vimentin in mesenchymal breast cancer cell lines (MDA-MB-435) resulted in more compact morphologies consistent with epithelial cells." (PMID 33691719, 2021). "p-Akt, p65NFκB, p-γH2AX, MCL1, GRP78 and VIM markers were expressed highest in the GFP-positive breast cancers while αSMA was expressed predominantly in the GFP-negative MSCs." (PMID 34239043, 2021).
breast carcinoma (continued). "Another reports also showed DOK7 and VIM hyper methylations in Spanish and Australian breast cancer patients, respectively." (PMID 33883026, 2021). "It is secreted by TAMs and triggers EMT and invasion of breast cancer cell lines through overexpression of vimentin and downregulation of E-cadherin." (PMID 34220337, 2021). "It has been reported that the abnormally high expression of vimentin in various epithelial cancers including prostate cancer, gastrointestinal tumors, and breast cancer is closely related to tumor growth, invasion, and poor prognosis." (PMID 35047006, 2021). "Repression of STARD13 by miR-125b in MCF-7 and MDA-MB-231 cells was responsible for EMT and metastasis in breast cancer cell lines via upregulation of vimentin and α-smooth muscle actin." (PMID 33477629, 2021). "Previous studies have reported the overexpression of vimentin in cases of breast cancer and HCC metastasis." (PMID 34577566, 2021). "Enhanced invasion of breast cancer cells was also shown to correlate with increased levels of N-cadherin and vimentin in CAFs." (PMID 33808627, 2021). "This was supported by another study showing that miR-9 expression in breast tumours is associated with E-cadherin loss and vimentin expression, thus playing a probable role in EMT in breast cancer." (PMID 33477629, 2021). "Metastasis was inhibited in breast cancer by WA via vimentin (motility inducing substance for cells) inhibition and induction of vimentin ser56 phosphorylation at a dose of 500 nM that was non-toxic to normal cells." (PMID 34946778, 2021). "Calycosin treatment inhibited epithelial-mesenchymal transition (EMT) of breast cancer cells by significantly increasing E-cadherin levels and decreasing N-cadherin, Vimentin, CD147, MMP-2, and MMP-9 levels through downregulation of BATF and TGFβ1." (PMID 34096887, 2021). "Activated human T cells are involved in the synthesis of IL-6, TNFα, and TGFβ which induce the expression of mesenchymal proteins such as fibronectin, vimentin, and Zeb1 in inflammatory breast cancer cells." (PMID 34220337, 2021). "As a member of the intermediate filament protein family, Vimentin is highly expressed in multiple cancers including breast cancer." (PMID 33653378, 2021). "Irradiation induced EMT process, which displayed a significant EMT phenotype with a down-regulated epithelial marker E-cadherin and up-regulated mesenchymal marker vimentin in comparison with untreated breast cancer cells." (PMID 34217266, 2021). "The increased expression of ALDH1 is related to the MET state of CSCS expressing lower levels of vimentin in breast cancer." (PMID 34638469, 2021). "Accordingly, vimentin silencing decreases pulmonary metastases in a pre-diabetic mouse model of mammary tumor progression." (PMID 34203746, 2021). "The expression level of vimentin increases in highly aggressive breast cancer cell lines, and this overexpression is closely related to migration and invasion." (PMID 32670437, 2020). "Although no expression of E- and N-cadherin was detected in any cancer cell model, a decrease in vimentin expression was observed in the brain-tropic breast cancer cells." (PMID 33182375, 2020). "In comparison to the isolated expression of vimentin alone, the dual expression of M marker vimentin and E markers cytokeratins 8 and 18, promoted invasiveness, metastasis and poor prognosis in breast cancer." (PMID 33207810, 2020). "Our data indicated that cryopreservation induced the improved migrating capability and invasion in breast cancer cells by upregulating the expression of Vimentin and F-actin and reorganizing intermediate filaments and microfilaments." (PMID 32787800, 2020). "Other targets of miR-30a in breast cancer have also been identified as potential links between this miRNA and the regulation of metastatic progression, including vimentin, MTDH, and Eya2." (PMID 32309442, 2020).
breast carcinoma (continued). "SP-141 also affects EMT-related proteins, such as β-catenin, vimentin, Twist and Snail and suppresses breast cancer migration in vitro and metastasis in vivo." (PMID 32456234, 2020). "This reduction of the cell motility by PIWIL4 downregulation has previously been described in breast cancer cells through an impairment of Vimentin and N-Cadherin." (PMID 32357464, 2020). "GSK1016790A produced a general trend in EMT marker mRNA levels in PMC42LA breast cancer cells with significant increases in Snail, vimentin, AXL, SERPINE1, and CD44." (PMID 33322037, 2020). "In the highly metastatic MDA-MB-231 breast cancer cell line, vimentin co-immunoprepicitates with endogenous p62." (PMID 33634029, 2020). "4T1 cells, derived from a murine mammary carcinoma, exhibit epithelial morphology, E-cadherin expression, and also some degree of vimentin positivity." (PMID 32053991, 2020). "Quercetin regulates the expression of EMT markers, such as E-cadherin, vimentin, and β-catenin, in head and neck cancer-derived sphere cells and breast cancer cells." (PMID 32050534, 2020). "Another study reported that intracellular mechanical homeostasis was interrupted in vimentin-knockdown breast cancer cells." (PMID 33330495, 2020). "CK18, vimentin, and N-cadherin expression in PB was statistically higher in the patients with recurrent breast cancer than in HVs (p = 0.031, p = 0.004, and p = 0.031, respectively)." (PMID 31947504, 2020). "In this study, we found that leptin downregulated expression of the epithelial marker E-cadherin and upregulated expression of the mesenchymal marker vimentin in breast cancer cells." (PMID 32836215, 2020). "In our study, the expression of E-cadherin and vimentin was reduced in breast cancer cells treated with chemerin alone." (PMID 32325994, 2020). "Of interest, we frequently observed both vimentin-positive breast cancer cells and vimentin-cytoplasmic BMP-2 co-positive cells in the BT-474/CTRL group." (PMID 32498363, 2020). "Overexpression of vimentin has been observed in carcinomas of the breast, lung, gastrointestinal and nervous system, and coincidentally, these cancers are generally associated with greater invasiveness and poorer prognosis." (PMID 31963677, 2020). "From that time, AKT-mediated phosphorylation of TWIST1 is already shown, we wanted to investigate the effect of our mutants on growth, metastasis, and induction of TWIST1 induced Vimentin and N-cadherin in breast cancer cells 4T1 and 67NR cells as well." (PMID 32922123, 2020). "In breast cancer, the presence of numerous vimentin breast cancer cells is detectable in poor differentiated carcinomas with negative prognosis." (PMID 32498363, 2020). "Recently, it was reported that miR-486-5p inhibited EMT by down-regulating SMAD2 and EMT regulators, vimentin and E-cadherin in breast cancer." (PMID 33374139, 2020). "Using confocal microscopy, we defined the vimentin/keratins ratio at the single cell level in representative breast cancer cell lines and patients’ CTCs." (PMID 33322610, 2020). "Mutual exclusivity data from the n = 1,105 breast cancer TCGA dataset revealed that PAPP-A has a significant tendency towards co-occurrence with mesenchymal markers Vimentin (VIM), SNAI1 (Snail), SNAI2 (Slug), Zeb1, Zeb2 and Twist1." (PMID 32792532, 2020). "Concerning the number of vimentin-positive breast cancer cells, a significant group effect was observed (p = 0.041)." (PMID 32498363, 2020).
breast carcinoma (continued). "Other studies have also shown that the high expression of P2Y6 receptor increases the expression of vimentin in breast cancer cells and promotes the metastasis of breast cancer." (PMID 33330466, 2020). "Compared with control cells, OC-treated breast cancer cells showed reduced levels of epithelial markers (E-cadherin) and increased levels of mesenchymal markers (vimentin, N-cadherin, α-SMA, Snail and Twist)." (PMID 32934344, 2020). "A subpopulation of CTC expressing TF and vimentin has also been observed in the blood of metastatic breast cancer patients." (PMID 32575608, 2020). "Our study demonstrates that S100P enhances cell proliferation by activating CCND1, and promotes cell migration and invasion through downregulating E-cadherin and upregulating Vimentin in breast cancer in vitro." (PMID 33042844, 2020). "This study showed that the expression of E‐cadherin was upregulated, while the expression of vimentin was downregulated in LHE‐treated breast cancer cells." (PMID 33133573, 2020). "The TGF-β1 treatment was sufficient to induce vimentin expression and render the cells capable of wound healing, in the case of epithelial cells, and invading through Matrigel, in the case of canine breast cancer cells." (PMID 31940801, 2020). "Overexpressing vimentin in MCF7 breast cancer cells reoriented microtubule polarity, increased cell directional migration, and EMT phenotypes." (PMID 33330495, 2020). "Triple-negative breast cancer cells, such as MDA-MB-231 cells, have an EMT morphology (presenting low expression of E-cadherin and high expression of vimentin) and a greater invasive capacity than luminal breast cancer cells (MCF7 and T47-D cells)." (PMID 33291240, 2020). "Overexpression of miR-138-5p inhibits EMT in breast cancer cells through up-regulating E-cadherin and down-regulating N-cadherin and vimentin." (PMID 32391554, 2020). "The treatment of breast cancer MCF-7 cell line with leptin leads to a remarkable increase in the expression of EMT markers (including vimentin and Snail) along with a downregulation of the epithelial marker E-cadherin." (PMID 33123472, 2020). "On the contrary, Vimentin, Snail and Slug were relatively highly expressed in both basal‐like breast cancer cell lines." (PMID 32510753, 2020). "It has been shown that enhanced expression of HSP70 is accompanied with activation of mesenchymal markers N-cadherin, MMP2, SNAIL, and vimentin and promotes metastasis of breast cancer." (PMID 33096691, 2020). "Increased expression levels of vimentin have been reported in various cancers, including breast cancer, prostate cancer, endometrial cancer, central nervous system tumors, gastrointestinal tumors, and malignant melanoma." (PMID 32670437, 2020). "The specificity of the antibodies for epithelial (EpCAM, E-cadherin, CK8, CK18, and CK19) and mesenchymal (vimentin, fibronectin, and N-cadherin) markers used in the negFACS-IF:E/M platform were initially validated in various breast cancer cell lines." (PMID 32296584, 2020). "Accordingly, we previously reported the existence of CTCs co-expressing vimentin and TF in the blood of breast cancer patients." (PMID 32152404, 2020). "We found that NR2F2 played a crucial role in insulin-mediated EMT in breast cancer cells by increasing vimentin and N-cadherin and inhibiting E-cadherin levels." (PMID 32631390, 2020). "Vimentin plays a key role in the EMT of breast cancer, and its knockdown results in a reduction in genes associated with invasion and breast basal-like phenotype." (PMID 32670437, 2020).